MCL1 (MCL1 apoptosis regulator, BCL2 family member)
Diseases named in the same sentence as MCL1 in open-access papers (continued):
Sharing a sentence is not in itself a finding about the gene and the disease.
tumor (continued). "Synergistic effects could be achieved through the combination of AMG-176 with venetoclax in AML tumor models and in primary patient samples at a tolerated dose, highlighting the potential for dual MCL1 and BCL2 inhibition." (PMID 33198338, 2020). "Moreover, the expression levels of proteins Mcl-1 and p-Chk1 in the tumor tissues were analyzed by immunohistochemistry." (PMID 32932732, 2020). "Additionally, mouse xenotransplant models confirmed that modification of Mcl-1 alternative splicing increased tumor cell death and suppressed tumor proliferation." (PMID 33052877, 2020). "The efficacy of this combination could even be enhanced by prior transient exposure to BCL-xL inhibitors which promote the binding of pro-apoptotic proteins (in particular BIM) from BCL-xL to MCL-1 and by this way augment the tumor MCL-1 dependency." (PMID 32722518, 2020). "Accumulated evidence shows that MCL1 expression confers tumor cells resistance to ABT-263." (PMID 32486166, 2020). "We observed that Mcl‐1 overexpression could inhibit Trametinib/TRAIL‐induced tumour cell death, while decreased Mcl‐1 increased Trametinib/TRAIL‐dependent apoptosis." (PMID 32352219, 2020). "This study highlights the importance of promoting ubiquitination-dependent Mcl-1 turnover might be an alternative strategy to enhance the anti-tumor efficacy of EGFR-TKI." (PMID 32276600, 2020). "Furthermore, combination of quizartinib with venetoclax was superior to combination with navitoclax plus AMG 176, suggesting that quizartinib elicits anti-tumor activity outside of its reduction of MCL1 levels." (PMID 33076970, 2020). "MCL-1 also protects CRC tumor cells from the apoptotic effects of targeted drugs." (PMID 33308268, 2020). "Finally, to evaluate the potential of MCL-1 as a druggable target, we treated tumour-bearing mice with the MCL-1 inhibitor S6384521." (PMID 32913197, 2020). "Thus, the anti-tumor effects of S63845 were considered to be the induction of apoptosis via MCL1 inhibition." (PMID 32152266, 2020). "The tumorigenicity assay in male severe combined immune-deficient mice was performed to investigate whether modification of Mcl-1 splicing via SBO treatment affected tumor cell apoptosis and growth in vivo." (PMID 33052877, 2020). "Our data identified PD-L1 as a novel tumor suppressor in aggressive EC cells and showed that loss of PD-L1 expression enhances the invasive abilities of EC cells by inducing EMT through the upregulation of MCL-1 expression." (PMID 33363153, 2020). "More importantly, the marked tumor suppression induced by DT2216 was associated with a more than 95% reduction in Bcl-xL levels, substantial decreases in Bcl-2 and Mcl-1 levels, and significant activation of caspase-3 and cleavage of PARP in the tumors collected from the mice." (PMID 32677976, 2020). "It has been suggested that MCL1 expression confers tumor cells resistance to ABT-263." (PMID 32486166, 2020). "Immunohistochemistry on tumor biopsies showed strong cytoplasmic expression of MCL-1 that could be correlated with tumor stage, lymph node metastasis and with inferior survival of CRC patients." (PMID 33308268, 2020). "Here we show that administration of ABT-737 can overcome the radioresistance in RPN2 overexpressed GBM cells, suggesting that inhibition of MCL1 could be a therapy strategy for GBM patients with abnormal tumor RPN2 expression." (PMID 32404045, 2020). "Therefore, the ratio between Noxa and Mcl-1 is an indicator for the apoptotic threshold of tumor cells." (PMID 32752193, 2020). "In mice, tumour progression is delayed upon pharmacologic or genetic inhibition of MCL-1." (PMID 32913197, 2020). "While modest suppression of tumor growth could be seen by targeting just BCLxL or MCL1, a deeper impact was observed by co-targeting both of these pro-survival proteins." (PMID 32913182, 2020).
tumor (continued). "Since our results indicate that BCL-xL reduction by A-1331852 potentiates regorafenib activity and low MCL-1 levels expose A-1331852 anti-tumoral activity against HCC tumor cells, we focused our attention on BCL-xL and MCL-1 alterations exhibited by human HCC tumors." (PMID 32024199, 2020). "Mechanistically, PD-L1 exerts the anti-tumor effects by downregulating MCL-1 expression." (PMID 33363153, 2020). "MCL-1 contributes to tumor cell survival by interfering with the apoptotic machinery." (PMID 33308268, 2020). "One the other hand, AURKA plays a pivotal role in tumor survival by provoking Bcl-2 and MCL-1, and anti-apoptotic factors levels, blocking Bax, Bim, PUMA apoptotic mediators activity, along with disruption of the mammalian Target of Rapamycin (mTOR) autophagy pathway." (PMID 32469983, 2020). "Additionally, overexpression of miR-135-3p or knockdown of MCL1 reversed the pro-tumor effect of FGD5-AS1." (PMID 32675387, 2020). "Furthermore, it is important to note the preferential expression of both BCL-XL and MCL-1 in tumor compared to the normal tissues, which provides a basis for BH3 mimetics to selectively target the tumor tissue." (PMID 31801952, 2019). "As the protein expression level and biological effect of the anti-apoptotic factors MCL1 and survivin (BIRC5) have been associated with phosphorylation of STAT3 in tumor cells, we examined the protein expression level of STAT3 target genes, including MCL1 and survivin." (PMID 31287013, 2019). "Treatment of tumor cell lines with AMG176 elicited an increase of MCL-1 half-life." (PMID 30813354, 2019). "We also show that SCCHN is dependent on both BCL-XL and MCL-1 for survival, which can be efficiently targeted to induce marked apoptosis and tumor shrinkage, suggesting that a combination BH3 mimetic therapy may offer significant benefits in SCCHN." (PMID 31801952, 2019). "Finally, we detected the level of Bcl-2 family anti-apoptotic protein Bcl-2, Bcl-XL, Mcl-1, and Survivin, these proteins were overexpressed in tumor cells and helped tumor cells avoid apoptosis." (PMID 31569691, 2019). "Likewise, it appeared that the levels of MYC and MCL1 were much higher in NSCLC tumor cells relative to adjacent normal lung cells, and CycT strongly decreased their levels in tumor cells." (PMID 30723259, 2019). "To gain insights into the underlying mechanism of apoptosis induction effect caused by Huaier (6 mg/ml), 5-FU (30 μg/ml), and their combination, we detected the expressions of two anti-apoptotic protein Mcl-1 and Bcl-2, which were considered a therapeutic target in tumor apoptosis process." (PMID 31391034, 2019). "Thus, ERK1/2 pathway inhibitors primed ERK1/2-dependent tumour cells to undergo an immediate activation of the canonical cell intrinsic apoptotic pathway following MCL1 inhibition." (PMID 31727888, 2019). "There is evidence that MCL-1 is an important target for tumor diagnosis and treatment." (PMID 30728351, 2019). "There is ample evidence that MCL-1 is an important tumor target." (PMID 30728351, 2019). "In addition, STAT3 is associated with tumor cell apoptosis through the regulation of BCL2, BAX, MCL1 and survivin (BIRC5)." (PMID 31287013, 2019). "Notably autonomic ganglia tumour cells which, like melanocytes, have neural crest developmental origin also exhibited a high MCL1:BCL-XL ratio." (PMID 31727888, 2019). "Addition of the CDK4/6 inhibitor LEE011 to BYL719 caused a simultaneous reduction of p-RB and p-S6, and a more complete inhibition of p-S6, leading to decreased expression of the pro-survival protein MCL-1, an induction of apoptosis, and an enhanced reduction of tumor growth in a PDX model of TNBC." (PMID 31101835, 2019).
tumor (continued). "The difference in the susceptibility of D-10-0021 MG, DM440, and SUM159-R113 cells to the 9.2.27-PE38KDEL, ABT combinations impelled us to examine the role of selected prosurvival (Bcl-xL and Mcl-1) and proapoptotic (Bim and Bax) Bcl-2 members in potentiating tumor cell death." (PMID 30625226, 2019). "Since BCL-XL and MCL-1 share a high degree of functional redundancy both in tumor survival and in normal cellular homeostasis, a combination of inhibitors targeting these proteins may result in some degree of toxicity to normal tissues." (PMID 31801952, 2019). "Mcl-1-mediated inhibition of senescence can enhance tumor growth." (PMID 31076590, 2019). "Importantly, the combination of ABT-263 with VU661013 potently inhibited growth of tumor cells cultured in monolayer similar to the growth inhibition seen with ABT-263 in combination with shRNA sequences knocking down Mcl-1." (PMID 31595181, 2019). "Furthermore, we identified that Mcl-1 plays an important role in H89/tetrandrine anti-tumor activity in vitro and in vivo." (PMID 29866132, 2018). "Tumor cells that escape senescence also rely on Bcl-XL and Mcl-1 signaling." (PMID 29731994, 2018). "MCL1 has been reported to limit tumor responses to chemotherapeutics and BH3 mimetic inhibitors." (PMID 29335437, 2018). "Therefore, strategies blocking Mcl-1 expression or activity used in combination with endocrine therapies would enhance tumor cell death." (PMID 29343814, 2018). "However, our data suggest that upon treatment resistance increased pro-apoptotic signals are thwarted by Mcl-1 upregulation, thus promoting tumor cell survival." (PMID 29343814, 2018). "Furthermore, inhibition of H3K9me3 resulted in elevated Bak, Bax and Bim expression level and inhibition of H3K4me3 led to decreased Bcl-x, FLIP and Mcl-1 expression levels in the tumor cells." (PMID 29409480, 2018). "Finally, USP13 inhibition reduced MCL1 protein abundance and thereby increased tumor cell sensitivity to BH3 mimetic inhibitor ABT-263." (PMID 29335437, 2018). "We subsequently investigated the impact of USP13-mediated MCL1 stabilization on tumor malignancy." (PMID 29335437, 2018). "This supported our hypothesis of a selective pressure against loss of MCL-1: while 6 of 7 WT mice and 11 of 11 HET mice developed RFP-positive tumours, only 2 of 8 HOM mice developed any RFP-positive tumours." (PMID 29339815, 2018). "Therefore, we propose that USP13 is a bona fide deubiquitinase for MCL1, a notion that is further supported by the endogenous interaction and correlative expression of USP13 and MCL1 only at protein levels in clinical tumor samples." (PMID 29335437, 2018). "A Western blot assay was used to detect MCL‐1 levels in xenograft tumor tissues." (PMID 30030896, 2018). "Further, we tested the utility of MCL1 si-NPs in combination with fulvestrant, because Mcl-1 expression was induced upon short-term fulvestrant treatment in culture and in vivo, and tumor cell death was increased upon combined treatment with fulvestrant and MCL1 si-NPs." (PMID 29343814, 2018). "Therefore, agents that reduce Bcl-2, Bcl-xL and/or Mcl1 expression combined with small molecule Trk inhibitors and agents that promote mitochondrial apoptosis, would be expected to kill TrkAIII expressing tumour cells." (PMID 29914559, 2018). "Low levels of apoptosis were detected in the excised tumours by immunohistochemistry for cleaved caspase 3 while a significant increase was seen in the UMI-77-treated tumours consistent with the on target effects of UMI-77 in MCL-1 inhibition and induction of apoptosis that we observed in vitro." (PMID 29339815, 2018). "Importantly, tumor samples from four independent PEL cases at the Northwestern Memorial Hospital since 2010 showed very high expression of MCL1 specifically in the KSHV-infected tumor cells." (PMID 30111820, 2018). "Thus, tumour cell survival in the context of increased DNA damage following Huwe1 deletion is partially dependent on increased levels of MCL1." (PMID 28003334, 2017).
tumor (continued). "In addition, AKT inhibition sensitized tumor cells to immune destruction by disrupting Mcl-1 mediated anti-apoptotic signaling." (PMID 29156850, 2017). "As apigenin induces apoptosis in tumor cells by modulating different kinds of signaling pathways, including downregulation of Mcl-1 mRNA, this apigenin Mcl-1 downregulation may enhance the ABT-263 antitumor activity." (PMID 28352231, 2017). "Subsequently, we measured the expression of miR-101 and c-met/MCL-1 in purified tumor tissues." (PMID 29312559, 2017). "Together, our data suggest that CDK9 inhibitors may have single-agent anti-tumour activity against a subset of SCLC that either carry c-MYC amplification or are MCL-1-addicted." (PMID 28714472, 2017). "Moreover, knockdown of MCL-1 has been considered as a novel strategy to enhance the effect of anti-tumor drugs including TRAIL." (PMID 29312559, 2017). "In addition, in vivo experiments showed that PVT1 knockdown repressed xenograft tumor growth, while Mcl-1 overexpression partially rescued xenograft tumor growth." (PMID 29254209, 2017). "Furthermore, a decrease in the apoptotic protein such as Bax 47, 48 and an increase in the anti‐apoptotic protein including Bcl‐2 as well as Mcl‐1 47, 49, regulated by miR‐139‐5p, also participates in the tumour process." (PMID 28780773, 2017). "Overexpression of HER2 commonly causes the resistance of apoptosis by increasing anti-apoptotic proteins (e.g., Bcl-2, Bcl-X/L, Mcl-1, and survivin) and decreasing the proapoptotic protein Bim and, thus, contributes to tumor progression and contributes to the resistance to chemotherapy." (PMID 28335434, 2017). "Treatment-induced elevation in p-ERK and Mcl-1 was confirmed in tumor lysates by western blotting." (PMID 27351224, 2016). "Conversely, exploring Bcl-xL inhibitors may be less promising in the context of mitotic drivers unless patients whose tumours have low Mcl-1 levels can be identified." (PMID 27512141, 2016). "Taken together with our observations, this suggests that patients whose tumours have high Bcl-xL/Mcl-1 ratios might be good candidates for Bcl-xL inhibitor trials in combination with antimitotic agents." (PMID 27512141, 2016). "Several strategies have been developed to reduce Mcl-1 expression within tumor cells." (PMID 27689327, 2016). "Silencing of Mcl-1 resensitized tumor cells to ABT-737 and decreased their resistance to anoikis." (PMID 26921175, 2016). "FBW7 exerts its tumor suppressor function by promoting the ubiquitination and degradation of various oncoproteins, including c-Myc, Mcl-1, cyclin E, and c-Jun, which regulate many cellular processes, for example, cell proliferation, cellular metabolism, differentiation, and apoptosis." (PMID 27167197, 2016). "Interestingly, USP9x has been reported to have tumor-promoting activity, acting via stabilization of the pro-survival protein MCL1 in hematological tumors." (PMID 27462448, 2016). "To assess whether the recurrence of tumor was due to an acquired mechanism of Bcl-2 antagonist resistance, such as an adaptation to Mcl-1 dependence, we retreated one mouse and assessed the other tumor for changes in Bim binding by co-IP." (PMID 26874859, 2016). "For this reason, there is great interest in the development of small molecule pharmaceuticals that inhibit MCL-1, with some compounds showing high specificity and potent anti-tumor effects in vitro, but the poor pharmacokinetics of these compounds limits their use in vivo." (PMID 27931239, 2016). "Furthermore, the anti-apoptotic genes Bcl-2, Bcl-xL and Mcl-1 were all independently prognostic of favourable outcome, which argues against a simple anti-apoptotic/tumor-promoting role for these genes." (PMID 27120789, 2016). "Next we tested if MCL-1 inhibition can potentiate the anti-tumor effects of vemurafenib in vivo." (PMID 27846237, 2016).
tumor (continued). "The development of an MCL1 inhibitor that can be applied in preclinical tumor models and possibly in clinical trials would allow this hypothesis to be tested." (PMID 27990281, 2016). "Accordingly, it has been shown that an elevated expression of MCL1 or BFL-1/A1 may mediate the resistance of tumor cells to ABT-737-mediated apoptosis." (PMID 27042160, 2016). "We and others have described that the use of such CRm could represent a possible way to limit Mcl-1 expression in vivo and to sensitize tumor-bearing mice to BH3-mimetics-induced death." (PMID 27689327, 2016). "Notably, several lines of evidence showed that Fbw7 acts as a tumor suppressor by targeting numerous pro-oncogenic proteins for ubiquitination and degradation such as c-Myc, c-Jun, Mcl-1 and cyclin E." (PMID 27713122, 2016). "In contrast, inhibition of Mcl-1 expression was shown in other tumor entities before." (PMID 27172899, 2016). "These preclinical data suggest not only that the YAP and Hippo signaling pathways culminate in an Mcl-1-regulated tumor survival pathway but also that nuclear YAP expression may be a biomarker to employ in FGFR-directed therapy." (PMID 26826125, 2016). "We found that MCL‐1 was up‐regulated in the tumour specimens." (PMID 27420766, 2016). "Here, we show that ROS promotes the degradation of Mcl-1 and survivin in the hypoxic tumor cells." (PMID 27270321, 2016). "However, the average volume of the tumors in the mice that were treated with vemurafenib and Mcl-1 siRNA was 292 ± 48.12 mm3, showing a notable suppression of tumor growth by more than 80%, as compared to control or vemurafenib treated group." (PMID 26497853, 2015). "Moreover, the tumor samples from patients (9, 13, 25, and 29) which received both dabrafenib and trametinib also demonstrated elevated expression of Mcl-1." (PMID 26497853, 2015). "Human genetics points to a selective advantage of MCL1-amplified tumor cells." (PMID 25909780, 2015). "Protection from apoptosis via overexpression of Mcl-1 in tumor cells may represent a significant barrier to the effectiveness of chemotherapeutic agents." (PMID 26078955, 2015). "It is also possible that anti-tumor efficacy might be achieved through partial inhibition of MCL-1, which could be less toxic." (PMID 25590800, 2015). "The IHC staining of tumor tissues obtained from cisplatin-treated A549 xenografts supported the in vitro results by showing a higher number of Bcl-2 and Mcl-1 stained cells in tumors derived from sc cells than those from IL-6si cells (quantification is shown on the right)." (PMID 26313152, 2015). "Of note, preliminary results from our group indicate that co-expression of miR-101 and a Mcl-1 form lacking the 3′ untranslated region (thus impeding the binding of Mcl-1 to miR-101) via hydrodynamic transfection leads to the impairment of miR-101 tumor suppressor activity in AKT/Ras and c-Myc mice." (PMID 25762642, 2015). "Importantly, Fbxw7α is considered a tumor suppressor protein primarily because Fbxw7α targets multiple well-known oncoproteins, including Cyclin E, c-Myc, c-Jun, Mcl-1, and Notch-1 for ubiquitination-mediated destruction." (PMID 26461473, 2015). "Mcl-1 expression was evaluated in the biopsied tumor samples by immunohistochemistry." (PMID 26497853, 2015). "Inhibition expression of Mcl-1 induces apoptosis of tumor cells." (PMID 26317515, 2015). "Moreover, the tumor weight in the mice treated with Mcl-1 siRNA and vemurafenib was reduced by more than 85%, consistent with tumor volume data." (PMID 26497853, 2015). "Therefore, Mcl-1 protein level is elaborately regulated in both normal and tumor cells, among which phosphorylation modification is a quite significant way." (PMID 24779770, 2014). "Interestingly, Fbw7 is often referred to as a tumor suppressor for its roles in regulating the degradation of potent oncogenes such as Cyclin E, c-Myc, c-Jun, Mcl-1, mTOR and Notch-1." (PMID 24912918, 2014).